PFKFB2 (6-phosphofructo-2-kinase/fructose-2,6-biphosphatase 2)
Description:
Synthesis and degradation of fructose 2,6-bisphosphate.
Synonyms: PFK-2/FBPase-2
Tractability: Small molecule: a structure with a bound ligand is known; a high-quality ligand is known. PROTAC: ubiquitination databases record sites on it; its protein half-life has been measured; a small molecule that binds it is known.
Target class: Enzyme
Gene: Protein-coding gene on chromosome 1 (207,034,366 to 207,081,243, forward strand). Ensembl gene ENSG00000123836.
Subcellular location (Human Protein Atlas): Nucleoplasm
Pathways (Reactome):
Metabolism: Regulation of glycolysis by fructose 2,6-bisphosphate metabolism
Gene Ontology:
Molecular function: 6-phosphofructo-2-kinase activity; fructose-2,6-bisphosphate 2-phosphatase activity; protein binding; protein kinase binding; ATP binding; catalytic activity; kinase binding
Biological process: fructose 2,6-bisphosphate metabolic process; glycolytic process; fructose metabolic process; gluconeogenesis; positive regulation of glycolytic process
Cellular component: 6-phosphofructo-2-kinase/fructose-2,6-biphosphatase complex; nucleoplasm; cytosol
Genetic constraint (gnomAD): Loss-of-function variants: 44 observed, 57.11 expected, observed/expected ratio (o/e) 0.77, 90% interval 0.6 to 0.99. The upper end of that interval is the gene's LOEUF score, 0.99, which puts it in group 4 of 6, group 1 being the genes least tolerant of losing a copy. Missense variants: 392 observed, 587.63 expected, observed/expected ratio (o/e) 0.67, 90% interval 0.61 to 0.73. Synonymous variants: 200 observed, 213.37 expected, observed/expected ratio (o/e) 0.94, 90% interval 0.83 to 1.05.
Homologues: Orthologues: chimpanzee PFKFB2 (99% identical), macaque PFKFB2 (99% identical), dog PFKFB2 (97% identical), pig PFKFB2 (97% identical), guinea pig PFKFB2 (95% identical), rabbit PFKFB2 (95% identical), rat Pfkfb2 (93% identical), mouse Pfkfb2 (93% identical), tropical clawed frog pfkfb2 (81% identical), zebrafish pfkfb2b (78% identical), zebrafish pfkfb2a (74% identical), Drosophila melanogaster Pfrx (55% identical), and 2 more. Paralogues in human: PFKFB3 (67% identical), PFKFB1 (63% identical), PFKFB4 (62% identical).
Diseases named in the same sentence as PFKFB2 in open-access papers:
PFKFB2 is named in the same sentence as 44 diseases in open-access papers, as found by Europe PMC text mining. Sharing a sentence is not in itself a finding about the gene and the disease. The quoted sentences say what the papers report.
ovarian carcinoma (16 papers, 2018 to 2025). A malignant neoplasm originating from the surface ovarian epithelium. "PFKFB2 increased expression levels were associated with shorter overall survival in ovarian cancer, showing a direct association with the long non-coding LINC00092." (PMID 30884810, 2019). "A previous study shown that LINC00092, activated by CXCL14-rich CAFs, drives ovarian cancer metastasis by modulating glycolysis via PFKFB2 interaction, underscoring a vital metabolic feedback loop between CAFs and cancer cell advancement." (PMID 39988592, 2025). "Knockdown of PFKFB2 increased the glycolysis rate and enhanced the effect of paclitaxel-based chemotherapy in breast and ovarian cancers." (PMID 36712687, 2022). "LINC00092 interacted with a glycolytic enzyme named 6-phosphofructo-2-kinase/fructose-2,6-biphosphatase 2 (PFKFB2) to modulate glycolysis levels and supportive function of CAFs, thereby facilitating ovarian cancer metastasis." (PMID 35222443, 2022). "LINC00092 enhances glycolysis in ovarian cancer by binding to glycolytic enzyme fructose-2, 6-biphosphatase (PFKFB2) and activating 6-phosphofructo-1-kinase (PFK-1) via PFKFB2 catalytic product fructose-2, 6-bisphosphate (F-2, 6-BP)." (PMID 32174794, 2020). "Reciprocally, the glycolytic phenotype augmented by LINC00092 and PFKFB2 in ovarian cancer cells helps CAFs to remain activated and facilitates metastasis in the tumor microenvironment." (PMID 33050576, 2020). "CAFs-secreted CXCL14 induces LINC00092 upregulation which promotes ovarian cancer metastasis by enhancing PFKFB-2 translation." (PMID 31448238, 2019). "LINC0009 interacted with 6-phosphofructo-2-kinase/fructose-2,6-biphosphatase 2 (PFKFB2) to induce a glycolytic phenotype in ovarian cancer cells." (PMID 30103384, 2018). "Importantly, in ovarian cancer, linc00092 maintains the local supportive function of CAFs by binding to 6-phosphofructo-2-kinase/fructose-2,6-biphosphatase 2 (PFKFB2) to promote glycolysis in cancer cells, thus contributing to cancer metastasis." (PMID 33213510, 2020). "In ovarian cancer patients, a positive correlation between LINC00092 and PFKFB2 protein expression was observed, which suggests that LINC00092 directly interacts with PFKFB2, maintains PFKFB2 enzyme stability, and modulates glycolysis during ovarian cancer progression and metastasis." (PMID 33050576, 2020). "Moreover, LINC00092 was demonstrated to promote the glycolysis of tumor cells and induce the metastasis of ovarian cancer cells by enhancing the expression of glycolytic enzyme PFKFB2 (6-phosphofructo-2-kinase/fructose-2,6-bisphosphatase 2) and combining with it." (PMID 33520725, 2020). "LncRNA LINC00092 interactes with 6-phosphofructo-2-kinase/fructose-2,6-biphosphatase 2 (PFKFB2) to sustain the CAFs-like features of fibroblasts within tumor microenvironment and promote ovarian cancer metastasis." (PMID 35087824, 2021). "In ovarian cancer, CXCL14 regulated LINC00092 which bound glycolytic enzyme fructose-2,6-biphosphatase (PFKFB2) to promote its metastasis." (PMID 33204328, 2020). "In ovarian cancer, LINC00092 lncRNA regulates phosphofructo-2-kinase/fructose-2,6-bisphosphatase 2 (PFKFB2), enhancing its expression." (PMID 31191327, 2019).
glioma (8 papers, 2019 to 2023). A benign or malignant brain and spinal cord tumor that arises from glial cells (astrocytes, oligodendrocytes, ependymal cells). "Moreover for ZBTB20 and PFKFB2 genes plausible link between genes alteration and glioma proliferation and invasion was underlined, especially in the context of glioma-associated cells." (PMID 31170943, 2019). "Analyses of quantitative real-time PCR confirmed that S/G deprivation significantly induced the mRNA expression levels of GLUT1, GLUT 3, HK2, and PFKFB2 in glioma stem cells (GSCs) and GBM cells, including U87MG, LN18, and A172." (PMID 38098117, 2023). "PFKFB2 had been found to have a key role in regulating tumor growth and survival in multiple cancer types, including gastric cancer, gliomas, and osteosarcoma." (PMID 32855654, 2020). "UCA1 positively regulates PFKFB2 expression in glioma cells by functioning as a sponge against miR-182, which directly targets PFKFB2." (PMID 33050576, 2020). "UCA1/miR-182/PFKFB2 axis could modify GBM-associated stromal cells-mediated glycolysis and invasion of glioma cells." (PMID 34178658, 2021). "LncRNA-UCA1/miR-182 axis by interacting PFKFB2 could induce a glycolytic phenotype in glioma." (PMID 33123468, 2020). "The expression levels of EMB, LDHA, SLC16A1, SLC16A3, SLC16A8, PARK7, and PFKFB2 were lower in 1p/19q Codel glioma than those in non-Codel glioma." (PMID 36698888, 2022).
osteosarcoma (8 papers, 2018 to 2024). A usually aggressive malignant bone-forming mesenchymal neoplasm, predominantly affecting adolescents and young adults. "The tumor suppressor genes PFKFB2 showed quite low expression in malignant cells, which was consistent with its role as a protective factor in osteosarcoma as predicted by bioinformatics." (PMID 39569192, 2024). "For example, PFKFB2 has been highly expressed in lung cancer, gastric cancer, retinoblastoma, osteosarcoma, and breast cancer." (PMID 37919747, 2023). "PFKFB2 is highly expressed in lung cancer, gastric cancer, melanoma, retinoblastoma, osteosarcoma, HCC breast cancer, and prostate cancer." (PMID 37919747, 2023). "Studies have reported that PFKFB2 plays a role in regulating the development of acute kidney injury;, and PFKFB2 can be targeted by miR-1297 to inhibit the proliferation of osteosarcoma." (PMID 35184643, 2022). "Studies have also found that the SLIT2/ROBO1 axis promotes the Warburg effect of osteosarcoma by activating the SRC/ERK/c-MYC/PFKFB2 pathway." (PMID 36387908, 2022). "Another observation highlighting the importance of PFKFB2 in metabolic reprogramming is its contribution to osteosarcoma development." (PMID 30234009, 2018). "The SLIT2/ROBO1 axis promotes proliferation, inhibits apoptosis and contributes to the Warburg effect in osteosarcoma cells via activation of the SRC/ERK/c-MYC/PFKFB2 pathway." (PMID 30234009, 2018). "Therefore, PFKFB2 is a key factor in the development of osteosarcoma and is closely related to the prognosis of osteosarcoma." (PMID 36387908, 2022). "Multivariate Cox regression analysis confirmed that these 8 identified genes, including 2 protective elements (SQOR and PFKFB2) and 6 hazardous factors (MAFF, COL5A2, FAM162A, UQCRB, SFXN4, and COX6A2), could independently predict the overall survival of osteosarcoma samples." (PMID 39569192, 2024).
breast cancer (7 papers, 2018 to 2025). A primary or metastatic malignant neoplasm involving the breast. "The gene-gene interactions of deregulated glucose related genes in breast cancer, and it was found that deregulated glucose related genes show high interactions with PFKFB2, PFKFB4, FBP2, PCK2, ADH5 and other genes involved in glucose metabolism." (PMID 38173442, 2024). "It has also been found that circCARM1, secreted by breast cancer stem cells (BCSCs), is crucial in breast cancer cell glycolysis through the miR-1252-5p/PFKFB2 signaling axis." (PMID 37914951, 2023). "In addition, circCARM1 served breast cancer stem cell exosomes as vectors to regulate breast cancer cell metabolic reprogramming through the miR-1252-5p/PFKFB2 pathway." (PMID 38324181, 2024). "BC stem cell exosome-derived circCARM1 played an important role in breast cancer cell glycolysis by sponging miR-1252-5p which regulated PFKFB2 expression." (PMID 37213665, 2023).
diabetes (7 papers, 2016 to 2025). "Dysregulation of PFKFB2 has been linked to several metabolic disorders, including diabetes, obesity, and cancer, making it a promising therapeutic target for these diseases." (PMID 38227599, 2024). "We have postulated that the loss of PFKFB2 under conditions such as diabetes could lead to decreased metabolic flexibility and contribute to pathology." (PMID 40310487, 2025). "Fourteen of the loci overlapped published GWAS loci for diabetes related traits and were used to identify causal associations of HK1 and PFKFB2 with HbA1c." (PMID 37679740, 2023). "For example, G6pc2, Pfkfb2, Ogdh1 and Cox6a2 were significantly affected by 4 weeks of diabetes but were unchanged by 24 h of hyperglycaemia." (PMID 27882918, 2016).
gastric cancer (7 papers, 2018 to 2024). A primary or metastatic malignant neoplasm involving the stomach. "PFKFB2 expression is also enhanced in human gastric malignant tumors, being associated with increased levels of HIF-1α dependent genes, vascular endothelial growth factor (VEGF) and Glut1, indicating that HIF-1α could be responsible for the induction of PFKFB2 expression." (PMID 30234009, 2018). "For example, circFLNA presents with upregulated expression in gastric cancer, and the circFLNA/miR-646/PFKFB2 axis is a potential therapeutic target for gastric cancer." (PMID 34852712, 2021). "Moreover, miR-613 modulates PFKFB2 to relieve the Warburg effect in gastric cancer." (PMID 38955795, 2024). "Interestingly, PFKFB2 was suppressed by miR‐613 in gastric cancer, which could further inhibit cell proliferation and invasion." (PMID 32337851, 2020). "In hepatocellular carcinoma and in gastric cancer MACC1 expression positively correlates with expression of 6-phosphofructo-2-kinase/fructose-2,6-bisphosphatase (PFKFB2) and of fatty acid synthase (FASN)." (PMID 33652667, 2021).
melanoma (7 papers, 2018 to 2025). A malignant, usually aggressive tumor composed of atypical, neoplastic melanocytes. "Recent phosphoproteomic studies have identified PFKFB2 as a downstream phosphorylation substrate of RSK in BRAF-mutant melanoma cells." (PMID 40872623, 2025). "RSK phosphorylates PFKFB2 to increase PFKFB2 activity and the glycolysis pathway, which accelerates the growth of BRAF‐mutated melanoma." (PMID 37143582, 2023). "RSK directly phosphorylates PFKFB2 to increase PFKFB2 activity and glycolysis, which accelerates the growth of BRAF‐mutated melanoma." (PMID 37143582, 2023). "PFKFB2 mRNA expression analysis in the CCLE database also showed that the melanoma cell lines are among the tumor types that express higher amounts of PFKFB2, which correlated with low DNA methylation detection at the PFKFB2 promoter." (PMID 36402789, 2022). "RSK has been previously shown to regulate PFKFB2 (6-phosphofructo-2-kinase/fructose-2,6-bisphosphatase 2) to maintain flux through glycolysis in melanoma cells." (PMID 32605013, 2020). "Oncogenic BRAF V600E has also been found to activate p90 ribosomal S6 kinase (RSK), which phosphorylates and activates PFKFB2, that then binds to 14-3-3 to promote glycolysis and melanoma cell growth." (PMID 30234009, 2018). "RSK directly phosphorylates PFKFB2, promoting glycolysis and melanoma development." (PMID 40872623, 2025). "Altogether, these data confirmed the contribution of PFKFB2/PFKFB3 to the survival response to metabolic stress in NRASQ61 mutant melanomas, revealing a link between the RAS and glycolytic pathways, which implies the regulation of PFKFB2 by BRAF and probably ERK proteins." (PMID 36402789, 2022). "Altogether, the data indicate that PFKFB2 is overexpressed in NRASQ61 mutant melanomas and might be involved in their specific response to GS." (PMID 36402789, 2022). "Furthermore, MAPK-activated RSK, which directly phosphorylates PFKFB2, is required to maintain glycolytic metabolism in BRAF-mutated melanoma cells." (PMID 30234009, 2018). "Glucose deprivation promoted the colocalization of PFK1 to F-actin in NRASQ61 but not in BRAFV600E mutant melanoma cells, suggesting that PFKFB2-increased kinase activity was associated with simultaneous PFK1 activation in an attempt to maintain the glycolytic pathway." (PMID 36402789, 2022). "Altogether, these data suggest the existence of a feedback loop upon metabolic stress in NRASQ61mutant melanomas between the RAS pathway and the glycolytic route, connecting BRAF, PFKFB2, PFK1, SOS1/2 and NRAS." (PMID 36402789, 2022).
glioblastoma (5 papers, 2019 to 2022). The most malignant astrocytic tumor (WHO grade IV). "In glioblastoma, CXCL14 in glioblastoma-associated stromal cells could induce glycolysis and invasion of glioma cells by regulating the UCA1/miR-182/PFKFB2 axis." (PMID 32083005, 2020).
Sepsis (5 papers, 2024 to 2025). Sepsis is defined as life-threatening organ dysfunction caused by a dysregulated host response to infection. "PFKFB2, which is significantly upregulated in sepsis, has also been implicated in promoting neutrophil inflammatory activation." (PMID 40761792, 2025). "In conclusion, HP is identified as a potential diagnostic indicator for sepsis patients, and HP promotes neutrophil inflammatory activation by regulating PFKFB2 in the glycolytic metabolism of sepsis confirmed by in vitro experiments." (PMID 38227599, 2024). "MD simulation and MST further revealed that ILA binds stably to PFKFB2, a pivotal kinase in regulating glycolytic flux and immune activation during sepsis." (PMID 40761792, 2025). "Moreover, as the 1st sepGIK of ILA, PFKFB2 plays an important immunoregulatory role in sepsis by participating in the glycolytic pathway." (PMID 40761792, 2025). "Notably, PFKFB2, differentially expressed across 12 sepsis datasets, exhibited strong binding affinity with 15 of the gut microbial metabolites." (PMID 40761792, 2025). "The results showed the mRNA and protein levels of HP and PFKFB2 were both up-regulated in sepsis." (PMID 38227599, 2024). "Thus, we suspect that there is certain relation among HP, PFKFB2, glycolysis and neutrophils in sepsis." (PMID 38227599, 2024). "We suspected that PFKFB2 might be the target gene of HP in the glycolysis of sepsis." (PMID 38227599, 2024). "Ultimately, by taking the intersection of the results from the three machine learning methods, we identified six feature genes in sepsis: CD81, CLU, GLRX, CKAP4, DPEP2, and BCL11B; and seven feature genes in atrial fibrillation: LDHB, CD81, PFKFB2, CKAP4, CXCR4, DPEP2, and RORA." (PMID 41359645, 2025).
pancreatic cancer (4 papers, 2021 to 2024). "In the GSE69528-DEGs, PFKFB2 is revealed to regulate glycolysis and cell growth of pancreatic cancer." (PMID 38227599, 2024). "A recent study from our research team showed the need for the Pfkfb2 isoenzyme in the proliferation and glycolysis of pancreatic cancer cells." (PMID 38813509, 2023). "Recently, it was found that PFKFB2 is also overexpressed in pancreatic cancer, and mRNA spliceosomes of different PFKFB2 are localized in the cytoplasm and nucleus, respectively, affecting F-2,6-BP levels, glycolytic activity, and cell proliferation." (PMID 36699061, 2022). "Pfkfb2 has been reported to play a special role in regulating glycolysis and proliferation in pancreatic cancer cells." (PMID 33829047, 2021).
prostate carcinoma (4 papers, 2013 to 2025). A carcinoma that arises from epithelial cells of the prostate gland. "Depletion of PFKFB2 expression resulted in a reduced glucose uptake and lipogenesis, suggesting that the induction of de novo lipid synthesis by androgen requires the transcriptional upregulation of PFKFB2 in prostate cancer cells." (PMID 24280138, 2013). "PFKFB2 has been shown to be upregulated as a consequence of the transcriptional changes orchestrated by the androgen receptor in prostate cancer cells, with possible control through the AR-CAMKII-AMPK signaling pathway." (PMID 24280138, 2013). "Abrogation of PFKFB2 expression in prostate cancer cells reduced both glycolysis and lipogenesis." (PMID 34572020, 2021). "Moreover, expression of PFKFB2 is induced in LNCaP prostate cancer cells after androgen treatment by the direct recruitment of the ligand-activated androgen receptor to the PFKFB2 promoter." (PMID 24280138, 2013). "Therefore, it is compelling to speculate that transcriptional upregulation of PFKFB2 by androgen receptor signaling in hypoxia may represent a potential mechanism by which prostate cancer cells could allosterically upregulate glycolysis in the absence of HIF-1." (PMID 34572020, 2021).
lung carcinoma (3 papers, 2021 to 2023). "Shikonin directly downregulates the expression of PFKFB2 in human lung cancer cells (A549 and H446), inhibiting the Warburg Effect and exerting anticancer action in lung cancer cells." (PMID 36339566, 2022). "PFKFB2 is related to the cell proliferation, invasion, and migration of lung cancer." (PMID 37919747, 2023).
myocardial infarction (3 papers, 2021 to 2025). Gross necrosis of the myocardium, as a result of interruption of the blood supply to the area, as in coronary thrombosis. "PFKFB2 is the heart-specific isoenzyme of PFK2 that is highly responsive to hypoxic-ischemic insults in vivo, such as myocardial infarction (MI)-induced acute ischemia." (PMID 34679684, 2021).